TNF (tumor necrosis factor)
Diseases named in the same sentence as TNF in open-access papers (continued):
Sharing a sentence is not in itself a finding about the gene and the disease.
infection (continued). "In 3 patients, the same TNFα blocker was reintroduced after the recovery from infection 3, 4.5 and 14 months, respectively, after TJA infection diagnosis." (PMID 20637100, 2010). "Despite this, the LPS-induced MPs failed to induce macrophage activation whereas PbA-infection induced MPs induced up-regulation of CD40 expression and production of TNF." (PMID 20126448, 2010). "During the early stage of the infection, secretion of pro-inflammatory cytokines (IFN-γ, TNF-α) and NO by macrophages provides the host protection by inhibiting parasitic development and helping the host to prolong specific immune defenses." (PMID 20169057, 2010). "TNFα expression was elevated 2.27- to 6.29-fold in the sera of H-PRRSV-infected pigs on days 4 (p = 0.000) and 7 (p = 0.000) post infection, respectively, compared with C levels." (PMID 20929578, 2010). "For discrimination of mild infection, elevated SOD-1 levels showed greater sensitivity than TNF-alpha (76% vs. 30% respectively; p<0.0001), with higher specificity (100% vs. 97%; p<0.0001)." (PMID 20386593, 2010). "In particular, the infection with M. smegmatis led to an increased p38 and ERK1/2 MAPKs activity in BMDMs which was necessary for increased TNF secretion." (PMID 20831789, 2010). "In kidney homogenates, only TNF-α levels were significantly reduced in S100A9 KO mice, 24 hours after infection with 4.5×108 CFU." (PMID 20976233, 2010). "In these isolates, TNF-α production followed a different pattern, namely, production of TNF-α was contained from the start of infection, and was significantly lower than that induced by the remaining isolates at day 1 after infection." (PMID 20500810, 2010). "We propose that IL-17 elicited during the infection reduces IL-12 production and T-bet expression, which, as a consequence, decreases the production of IFN-γ, TNF-α, and chemokines." (PMID 20169058, 2010). "In this study cytokine quantification showed that although at day seven post-infection the levels of IFN-γ and TNF increased in mice infected with 124A, on day three the levels of IFN-γ were lower, comparing with mice infected with 140A." (PMID 20405013, 2010). "In active TB, macrophages release pro-inflammatory cytokines (IL-1, IL-6, TNF-α) in response to mycobacterial proteins and glycolipids, resulting in CD4 and CD8 T lymphocyte recruitment and activation at the site of infection and systemically." (PMID 20179751, 2010). "Cells from infected lungs, taken at week 6 or week 43 post infection, were stimulated with TB10.4 3–11 or TB10.4 74–88 prior to staining with anti-CD4, -CD8, -IFN-γ, -TNF-α and –IL-2." (PMID 19529765, 2009). "Here, we demonstrate that vMyxM013-KO infection of THP-1 cells also induces other cytokines and chemokines (TNF, IL-6, and MCP-1) that are regulated by the NF-κB pathway, in addition to the cytokines controlled by the caspase 1/inflammasome complex." (PMID 19851467, 2009). "Inflammatory cytokines produced by innate immune cells including TNF-α, IFN-γ, IL-12 and IL-18 are also important for curtailment of infection during the first week before onset of adaptive immunity." (PMID 19852827, 2009). "This activation is probable due the greater expression of FT induced by TNF-α and IL-6 whose level in serum and BAL were singnificantly increased between 8 and 48 h post-infection." (PMID 19835595, 2009). "Interferon gamma (IFN-γ) and tumor necrosis factor (TNF) are the key cytokines of the murine host response, and are absolutely required to control infection." (PMID 19543527, 2009). "We next stimulated CD20-depleted lymph node cells taken from SIV-naïve monkeys or monkeys at 14 days post infection in the same manner, this time analyzing cells for expression of IFN-α and TNF-α." (PMID 19424421, 2009).
infection (continued). "Alternatively, enhanced infection of microglia may increase proinflammatory responses resulting not only in enhanced recruitment of T cells and monocytes, but also increased local production of neurotoxic factors such as TNF, nitric oxide, oxidative radicals, and matrix metalloproteases." (PMID 19798426, 2009). "We thus next examined the levels of TNF, IL-1β, IL-2, IL-6, IL-10, and MCP-1 (also known as CCL2) in human PBMC infected by CDC1551, HN878, and HN878 pks1-15::hyg 2 and 4 days post-MTb infection." (PMID 19568431, 2009). "rhodesiense-infected mice treated with cordycepin and deoxycoformycin starting 20 days after infection contained diminished levels of IFN-γ, IL-1β, IL-6 and TNF-α mRNA compared to untreated infected controls when measured 10 days after treatment." (PMID 19652702, 2009). "Specifically, the induction of inflammatory molecules such as TNF, IL-6, and MCP-1 by active MTb infection is important for inhibition of TB disease progression, while at the same time these same molecules enhance HIV-1 replication." (PMID 19568431, 2009). "Effect sizes of louse infection grade on the most intense responses (TLR2 and TLR9) and on total TNF-α (summed over all receptor-ligand combinations), TIR, were striking." (PMID 19386086, 2009). "Analysis of BAL fluid demonstrated a significant reduction in secretion of TNF in the lungs of TLR2−/− and MyD88−/− mice compared to control mice at 5 days post-infection." (PMID 19936231, 2009). "All genes play major roles in immune response during infection including cytokines (IL8, IL6, IL10, IL1B, and TNF) and SAA3 (an acute-phase protein), as well as PMN adhesion selectin-L (SELL) and LYZ (involved in anti-microbial defense)." (PMID 19925655, 2009). "The severity of human infections with H5N1 virus in 1997 was partly due to the resistance of these viruses to interferons and TNFα during the host immune response." (PMID 21994553, 2009). "Quantitation of TNF-α, IP-10 and RANTES in culture supernatants from infected macrophages collected at different post-infection time points." (PMID 19462010, 2009). "Similar effects occur in LPS-stimulated dendritic cells, where infection blocks upregulation of MHC class II and costimulatory molecules in addition to TNF-α and IL-12." (PMID 19859561, 2009). "Macrophages harvested from TLR1−/− and TLR6−/− mice expressed TNF, IL-6, MCP-1, and IL-10 in response to LVS infection in vitro at comparable or higher levels than B6 mice." (PMID 19936231, 2009). "Infection with HIV induces immune activation with high levels of circulating cytokines, such as tumor necrosis factor-alpha (TNF-α), interleukin-6 (IL-6), IL-10, and some chemokines." (PMID 19852800, 2009). "In the infected mice (day 7 post infection), upon restimulation with SIINFEKL peptide, the OT1GFP cells synthesize effector cytokines such as IFN-γ, TNF-α and expressed increased levels of granzyme-B indicating that they are poised for cytolysis." (PMID 19578440, 2009). "In contrast, MV infection of primary human macrophages (pHMs) triggers induction of both TNF and type I IFN that prevents permissive infection." (PMID 18617992, 2008). "The infected mice secreted significant amount of proinflammatory cytokines like TNFα and MCP-1 and high amount of IFNγ, IL-1 and IL-6 at 24 h post infection." (PMID 18937835, 2008). "To further investigate the role of TLR2 during infection with S. pneumoniae PLN, we determined TNF-α, IL-1β, IL-10, MIP-2, KC and MPO levels in whole lung homogenates obtained 24, 48 and 72 h after inoculation." (PMID 17711480, 2008). "This would suggest a potential role for TNF-α in the maintenance of productive granulomas which may limit the spread of bacteria in chronically infected hosts, or, alternatively, in direct or indirect microbicidal or bacteriostatic activities at the sites of infection." (PMID 18823549, 2008).
infection (continued). "Our previous studies demonstrated that PRV-induced bladder pathophysiology was dependent upon TNF, so we examined the role of TNF in pelvic pain responses by quantifying pelvic tactile sensitivity in TNF−/− and TNFR1/2−/− mice following PRV infection." (PMID 18461160, 2008). "A variety of cytokines and chemokines were measurable during infection including: GRO, IL-1β, IL-6, IL-10, IL-12, GM-CSF, TNFα, MDC, and IL-8." (PMID 17257430, 2007). "IL-12 is also required for resistance to viral infections by stimulating TNF-α and IFN-γ production from inflammatory effector cells, which act synergistically to control infection." (PMID 23675015, 2007). "TNFα and IL6 levels were lower in TLR2 KO mice than in WT mice, especially at 72 h after infection (p < 0.05 and p < 0.001, respectively)." (PMID 17676990, 2007). "After infection, activated macrophages produce interleukin (IL)-12, which in turn stimulates CD4 T cells to produce Th1 cytokines (IFN-γ and TNF-α), thus linking the innate and adaptive immune responses." (PMID 17655752, 2007). "Many authors target finding proinflammatory markers of infection and SIRS other than the CRP, such as PCT, IL-1, IL-6, or TNFα." (PMID 17598889, 2007). "Briefly, by crossing RIP-LCMV-GP mice with Tet-TNFα mice we were able to control (i) the onset of the autoimmune process by infection with LCMV and (ii) the expression of TNFα in the β-cells by removal of doxycycline from the diet." (PMID 23675028, 2007). "Experimental evidence has revealed that tumor necrosis factor (TNF) plays a major role in host defense against Mtb in both active and latent phases of infection." (PMID 17953477, 2007). "TNF-α up-regulates MHC class II and the costimulatory molecules CD80 and CD86 on antigen presenting cells following infection or adjuvant treatment." (PMID 23675015, 2007). "In addition, production of TNF-α and IL-10 after stimulation with ES products differed by infection status, with hookworm-infected individuals producing significantly less, which might serve as a mechanism to minimize intestinal inflammation at the site of worm attachment in infected patients." (PMID 17576364, 2007). "Bacterial load and TNF in TLR2-/-, CD14-/- and TLR2-/-/CD14-/- mice was assessed simultaneously in all knockout mice after infection and values in knockout strains were compared to those in wt mice." (PMID 17428319, 2007). "Many studies have evaluated the usefulness of various markers of infection in different septic conditions – C-reactive protein (CRP), procalcitonin (PCT), TNFα, and IL-6, IL-8, and IL-10." (PMID 17598889, 2007). "In B6 mice 42 d after infection, PMA and ionomycin treatment induced a significant percentage of CD8 T cells to express IFNγ, TNFα, or both cytokines." (PMID 16733540, 2006). "We therefore conducted a long-term infection study in mem-TNF mice and compared it to WT mice infected with 100 CFU (intranasal route), a condition where TNF-KO mice die within 4–5 weeks." (PMID 16285886, 2005). "Pro-inflammatory TNFα, CCL2 and CXCL8 are important in maintaining a balance between recruitment of other macrophages and also T cells to restrict infection." (PMID 16001981, 2005). "A few hours after the type I IFN and TNF response, macrophages react upon HSV infection with production of IL-12, which is seen from 8 to 12 hours after infection and on." (PMID 16076403, 2005). "BAL concentrations of TNF-α, IFN-γ, MIG, RANTES, and MIP-1α followed similar dynamics in both strains of mice during the acute phase of the infection." (PMID 15916706, 2005). "TNF-α, IL-2, IL-4, IL-10, and IL-12p70 were not produced at 4 h post-infection with any of the bacterial strains, in either HT-29 or Caco2 cell lines (data not shown)." (PMID 41459941, 2026).
infection (continued). "Analysis of differentially expressed genes in the LC group compared with the CC group at day 90–180 after infection identified an increase of multiple proinflammatory markers, such as IL6, NLRP3, TNF, JAK2, CSF2, IL1B and IL10, in the LC compared with the CC group." (PMID 41388153, 2026). "Phenotypic analysis revealed that CD4+ T cellsexpressed IL-10 during infection across groups, but only ST2–/– infected mice showed higher expression intensity, measured as themean fluorescence intensity (MFI) of TNF-α and IFN-γ,indicating a shift toward a proinflammatory phenotype." (PMID 41365681, 2026). "Regardless of sex, infection induced upregulation of IL‐10, IL‐8, and TNF, alongside downregulation of CCL2 and IL‐18 in the supernatant of infected cells." (PMID 41546136, 2026). "Activation of FcγRs in the absence of infection typically promotes inflammatory responses via cytokines like IL-1β and TNF-α." (PMID 41485094, 2026). "Enrichment analysis indicated that Qufushengji hydrogel may intervene in immune-inflammatory responses, metabolic complications, and pathogen infection-related mechanisms by modulating AGE-RAGE, TNF, and other pathways." (PMID 41650101, 2026). "The infection induces a specific cytokine response characterized by an increase in the secretion of IL-8 and tumor necrosis factor (TNF)-α, but not of IL-6." (PMID 42138646, 2026). "Infection of murine macrophage J774A1 cells with L. donovani parasites is accompanied by production of pro-inflammatory cytokines IL-12 and TNF-α as well as the production of reactive nitrogen species (RNS) like nitric oxide, which would restrict parasite survival and proliferation." (PMID 41347503, 2026). "This study primarily investigates the correlation between inflammatory cytokines TNF-α, IL-6, and IFN-γ with DFI and further analyzes their relationship with infection severity, aiming to provide clinical guidance for early intervention, thereby improving patient prognosis and quality of life." (PMID 40677522, 2025). "Studies have shown that if the infection is not completely cleared from the body, it can lead to the continuous production of pro-inflammatory cytokines such as IL-1β, IL-6, IL-8, and TNF-α, which can limit the formation of granulation tissue and microvessels." (PMID 40529353, 2025). "Furthermore, infection, particularly with SFV/TNFα, selectively upregulated the expression of Marco—a scavenger receptor gene, associated with the poor prognosis in many types of cancers." (PMID 40547518, 2025). "For most of these infection models, IFN-γ contributed to the disruption of the BBB through downregulation of tight junctions, whereas in the WNV model, it was dependent on TNFα signaling." (PMID 40450318, 2025). "Polarized M1 THP-1 macrophages were resistant to TcpC’s influence on IL-1β but not TNFα or IL-6 secretion during an infection with CFT073." (PMID 41310197, 2025). "The mRNA expression of IL-29, TNF-α and IFN-β for the G4 swine viruses were similar to the level achieved in G1, whereas the expressions of ISG15 and MX1 were particularly high in H1N1/pdm/09 infection." (PMID 40742730, 2025). "Moreover, gEV exposure elevated TNF-α and RANKL expression in the bloodstream, as observed in GV infection." (PMID 40284791, 2025). "In the infection of human monocytic cell line THP-1 cells with the N. caninum dense granule protein 7 knock-out (NcGRA7KO) parasite and the parental strain Nc1, production of IL-1β and TNF-α, phosphorylated NF-κB p65 were measured." (PMID 41357231, 2025). "The levels of TNF-α, IL-6, IFN-γ, IP-10, MCP-1, and CCL3 were markedly elevated in the vehicle group, indicating that following infection with the influenza viruses, the lung tissues produced a plethora of proinflammatory mediators, thereby establishing an inflammatory milieu within the lungs." (PMID 40283905, 2025).
infection (continued). "Furthermore, the expression of TNF-α and CCL20 were notably higher following infection with P. verrucosa compared to the strains of P. submersa and P. americana (p < 0.05)." (PMID 40727705, 2025). "SRT1720 reduced plasma IL-6 and TNF-α levels at 42 h after infection, while not affecting plasma IL-12 or IFN-γ." (PMID 41096578, 2025). "The distinctive elevation of serum HBP, TNF-α, IL-6, and CRP levels in children with severe adenovirus pneumonia as well as those with poor prognosis underscored the central role of inflammatory pathways in the pathogenesis and prognosis of this infection." (PMID 40963970, 2025). "This mouse model showed detectable viral SARS-CoV-2 RNA and significantly elevated levels of pro-inflammatory interleukins (e.g., IL-6) and tumor necrosis factor-alpha (TNF-a) in the lung tissues 4 days, but not 15 days, after infection." (PMID 41472298, 2025). "This suggests that TNF components are not essential to mosquito survival, although under certain physiological conditions, such as infection, that TNF does contribute to mosquito fitness." (PMID 40608824, 2025). "In the case of infections with atypical pathogens, their concentration increases, but it is not as notable as for TNF-α." (PMID 40647668, 2025). "Later during infection, however, tlr4 mutant mice had elevated, albeit not significantly higher, amounts of TNF-α, IL-1α, and IL-6 relative to WT mice, consistent with persistent infection." (PMID 40817088, 2025). "Compared to the baseline infection, the no treatment group (n = 7) experienced a 2.2-fold increase in TNF-α expression (62.2 ± 27.6 pg/cornea, P = 0.019) and a 3.1-fold increase in IL-8 levels (606.7 ± 205.6 pg/cornea, p = 0.006)." (PMID 41384791, 2025). "Supplementation with Vpx-VLPs not only enhanced infection by over 100-fold, but was also sufficient to trigger IL-1β secretion even in the absence of TNFα." (PMID 40920844, 2025). "Constantly elevated TNF-alpha, IL-1 beta, IL-1 alpha, IFN gamma, and IL-6 levels throughout infection with both viruses might be linked to sustained apoptosis." (PMID 40358160, 2025). "The requirement for the intradermal infection followed by TNF-α neutralization to induce dissemination to the lungs is because mice lacking Nos2 are unable to control an aerosol infection with Mtb type strain H37Rv and rapidly succumb." (PMID 41279700, 2025). "More specifically, TNF-α expression increased in monolayers after 1h and continued to rise after 2h, in contrast with 3D cells that presented TNF-α mRNA levels significantly elevated at 1h, but did not increase from 1h to 2h of infection." (PMID 40051624, 2025). "In addition, J774A.1 macrophages were infected with H37Rv (multiplicity of infection [MOI] = 5), and the mRNA expression of cytokines TNF-α, IL-2, IL-12, and IFNγ was detected, which was consistent with the results of LPS treatment." (PMID 40396746, 2025). "In order to conduct a more thorough investigation into whether an infection by L. major results in PKR/NF-kB-dependent TNF expression, RAW 264.7 cells were subjected to infection for a period of 4 h." (PMID 40521699, 2025). "Infection studies using recombinant Msmeg strains expressing Mtb PE18 and PPE26 proteins confirmed these findings, demonstrating enhanced production of proinflammatory cytokines such as TNFα, IL6, and IL12." (PMID 39949767, 2025). "By contrast, the gingipains absence in the W83 ∆KRAB mutant did not affect the secretion of other cytokines (i.e., TNF-α and IL-6) after 24 h of infection." (PMID 39936030, 2025). "Furthermore, XY018 treatment reduced inflammatory cell infiltration and decreased viral mRNA levels, as well as TNF-α, IL-1β, and IL-6 mRNA levels in the lung tissues of H5N1 virus-infected mice on day 3 after infection." (PMID 41134862, 2025).